SAE1 (SUMO1 activating enzyme subunit 1)
Diseases named in the same sentence as SAE1 in open-access papers (continued):
Sharing a sentence is not in itself a finding about the gene and the disease.
tumor (continued). "We conducted a correlation analysis between the expression of SUMO2 or SAE1 and that of other genes in tumor samples of the TCGA_LIHC and GSE14520 datasets to understand the function of SUMO2 and SAE1 in HCC." (PMID 35859792, 2022). "Taken together, the overexpression of SAE1 in HCC contributed to aberrantly activated cell cycle and promoted tumor cell proliferation." (PMID 35859792, 2022). "Recent studies indicate that SAE1/UBA2, a heterodimer that catalyzes the first step of the SUMOylation cascade, is involved in regulating tumor growth and metastasis." (PMID 32938830, 2020). "Previously, shRNA-mediated inhibition of SAE2, or its binding partner SAE1, in HMECs overexpressing a MYC-oestrogen receptor fusion transgene was shown to induce spindle defects, polyploidy, apoptosis and tumour regression." (PMID 31455158, 2019). "Additionally, SAE1 companied by E2 UBC9 and E3 ligase PIAS4 mediates AKT SUMOylation majorly at K276, regulating AKT activation and promoting tumor progression, which can be reversed by SENP1." (PMID 37415251, 2023). "Consistent with the vital role of SUMO proteins and the UBC9 in SUMOylation, we further demonstrated that similar to SAE1, the expression levels of SUMO1, SUMO2, and UBC9 were upregulated in the HCC tissues compared to their non-tumor paracancerous counterparts." (PMID 33477333, 2021). "Moreover, SENP1, USPL1, SENP2, SENP5, SAE1, UBA2, and UBE2I had differential expressions with different tumor grades." (PMID 34267779, 2021). "Our results indicate that regardless of excluded cases, the median expression of SAE1 mRNA remained significantly upregulated in the tumor samples (~1.1-fold, p < 0.0001)." (PMID 33477333, 2021). "Further subgroup analyses indicated that SAE1 and UBE2I had differential expressions with different stages, while SENP1, USPL1, SENP2, SENP5, SAE1, UBA2, and UBE2I had differential expressions with different tumor grades." (PMID 34267779, 2021). "The results showed that the depletion of Circ-RAPGEF5 significantly impaired the process of AKT SUMOylation and that this process could be rescued by SAE1, suggesting that Circ-RAPGEF5-mediated SUMOylation plays an important role in tumor formation and progression." (PMID 37705041, 2023). "We analyzed the methylation level of all SAE1 CpG sites between normal and tumor samples in the TCGA_LIHC dataset to rule out the possibility that methylation at a specific CpG site of SAE1 might be strongly correlated with SAE1 mRNA expression." (PMID 35859792, 2022). "Functionally, SAE1 promotes the proliferation and invasion of HCC cells and inhibits apoptosis, whereas the absence of SAE1 blocks the tumor cell cycle." (PMID 37705041, 2023).
infection (4 papers, 2015 to 2019). The state of being infected such as from the introduction of a foreign agent such as serum, vaccine, antigenic substance or organism. "In cells infected with Shigella, the E1 activating enzymes SAE1 and SAE2 were readily detected in equal abundance up to 3 hours after infection." (PMID 25848798, 2015). "Our data show that Neddylation genes such as APPBP1 (2.78-fold), UBA3 (5.49-fold), UBC12 (2.31-fold) and SUMOylation genes such as SAE1 (4.69-fold), SAE2 (3.12-fold), UBC9 (2.22-fold), SUMO1 (6.36-fold) were significantly upregulated as early as the 2-h time point after infection." (PMID 31642343, 2019). "In the case of AIEC, we showed that expression levels of UBC9 as well as SAE1 and SAE2 enzymes were not significantly modified upon infection." (PMID 30634511, 2019).
SAE1 also shares sentences with these, for which no sentence is quoted: gout (2 papers); metastatic cancer (2); Myalgia (2); ovarian carcinoma (2); alveolar rhabdomyosarcoma (1); breast invasive carcinoma (1); cervical squamous cell carcinoma (1); chondrosarcoma (1); chordoma (1); colon adenocarcinoma (1); endocervical adenocarcinoma (1); familial amyloidosis (1); fibromyalgia (1); gastric tumor (1); head and neck squamous cell carcinoma (1); idiopathic inflammatory myopathies (1); inflammation (1); lung squamous cell carcinoma (1); lymphoid neoplasm (1); multiple myeloma (1); myocarditis (1); neurological disorders (1); pancreatic adenocarcinoma (1); pneumonia (1); polymyalgia rheumatica (1); Pulmonary interstitial disease (1); renal carcinoma (1); skeletal dysplasia (1); spondyloarthritis (1); thyroid cancer (1).
A further 2 diseases each share a sentence with SAE1 in 1 paper.